RNU6-844P (RNA, U6 small nuclear 844, pseudogene)
Gene: Small nuclear RNA gene on chromosome 15 (57,405,074 to 57,405,175, reverse strand). Ensembl gene ENSG00000252984.
Homologues: Orthologues: chimpanzee U6 (100% identical), macaque U6 (92% identical), mouse Gm23423 (81% identical), rat LOC120103214 (79% identical), guinea pig U6 (75% identical), dog U6 (72% identical). Paralogues in human: RNU6-1042P (89% identical), RNU6-166P (84% identical), RNU6-242P (84% identical), RNU6-38P (84% identical), RNU6-409P (84% identical), RNU6-590P (84% identical), RNU6-891P (84% identical), RNU6-1145P (83% identical), RNU6-116P (83% identical), RNU6-15P (83% identical), RNU6-310P (83% identical), RNU6-382P (83% identical), and 1285 more.